SOX30 (SRY-box transcription factor 30)
Diseases named in the same sentence as SOX30 in open-access papers (continued):
Sharing a sentence is not in itself a finding about the gene and the disease.
tumor (continued). "Consistent with our theory, the protein expression of MMP7 and CCND1 were downregulated in a SOX30-overexpressing cell line and xenograft tumors; MMP7 and CCND1 expression were increased significantly in SOX30-overexpressing cells, or tumor tissue after DSP or JUP expression was blocked." (PMID 29855376, 2018). "To further investigate whether upregulation of DSP, JUP and DSC3 are necessary for SOX30-medicated tumorigenesis and metastasis in vivo, we utilized a xenograft tumor model using these stable cell lines." (PMID 29855376, 2018). "Moreover, clinicopathological analyses showed that low SOX30 expression was positively related to an advanced tumor, node, and metastasis (TNM) stage." (PMID 29880037, 2018). "Different associations of SOX30 expression with metastasis in ADC and SCC patients suggested that SOX30 might play different roles on tumor metastasis in ADC and SCC." (PMID 30514297, 2018). "As SOX30 plays different roles on tumor metastasis by inconsistent mechanism in ADC and SCC, we assessed whether the different functions of SOX30 contribute the overall survival (OS) of ADC and SCC patients differently." (PMID 30514297, 2018). "Taken together, these results suggested that the “SOX30-desmosomal genes axis” may act as tumor suppressor in ADC." (PMID 29855376, 2018). "Therefore, SOX30 expression was decreased in CRC tumor tissue." (PMID 35836594, 2022). "In conclusion, tumor SOX30 negatively associates with LYN metastasis, T stage, N stage, and TNM stage while positively relates to accumulating OS in CRC patients, suggesting SOX30 might be a possible biomarker of progression and prognosis of CRC." (PMID 35836594, 2022). "Interestingly, SOX30 exerts its anti-tumor effect through Wnt/β-catenin signaling inactivation." (PMID 31889959, 2019). "Therefore, we hypothesized that SOX30 may inhibit tumor progression through upregulation of the desmosomal gene expression in ADC but not in SCC." (PMID 29855376, 2018). "SOX30, in contrast to SOX17 and SOX18, exhibited suppressed expression at both mRNA and protein levels across tumor regions." (PMID 41373817, 2025). "Spatial transcriptomics revealed SOX18 enrichment at tumor cores and invasive borders, co-localizing with MEF2C, VCAM1, and p-STAT3 in vascular and stromal niches, while SOX30 expression remained low across all tumor regions." (PMID 41373817, 2025). "We demonstrated statistically significant differences in expression between normal and primary tumor tissues for SOX6, SOX8, SOX21 and SOX30 genes and pointed to SOX6 as the one that met the independent diagnostic markers criteria." (PMID 38132438, 2023). "SOX30 protein and mRNA expressions were both decreased in CRC tumor tissue compared to adjacent tissue (both P < 0.001)." (PMID 35836594, 2022). "In summary, SOX18 and SOX30 play divergent roles in NSCLC progression: SOX18 functions as a pro-oncogenic factor driving angiogenesis and tumor–stroma interactions, while SOX30 acts as an epigenetically silenced tumor suppressor." (PMID 41373817, 2025). "Although SOX30 contributes to tumor suppression, current evidence does not support its role as a singular ‘key’ regulator of tumorigenesis." (PMID 41373817, 2025). "Furthermore, there were 46 CRC patients’ tumor SOX30 mRNA expression ≤0.392 and 47 CRC patients’ tumor SOX30 mRNA expression >0.392." (PMID 35836594, 2022). "To determine the expression level of SOX30 in tumor tissues of different NSCLC histological types, we probed SOX30 expression using immunohistochemistry (IHC) in lung tumor tissues of 540 NSCLC patients including 275 ADC, 231 SCC and 34 LCC on tissue microarrays." (PMID 30514297, 2018). "Expression levels of SOX30 were markedly lower in BC cells and tumor tissues than in adjacent noncancerous tissues." (PMID 29880037, 2018). "Another remaining question is that SOX30 do not affect the tumor metastasis in SCC, how it can become an unfavorable prognostic factor for OS of SCC patients?" (PMID 30514297, 2018).
tumor (continued). "While in early-stage SCC patients, SOX30 has no role on tumor-metastasis and Wnt/CTNNB1-signaling duo to not binding to CTNNB1 promoter and results in an unfavorable prognosis of the patients." (PMID 30514297, 2018). "Furthermore, tumor SOX30 protein expression was positively correlated with overall survival (OS) (P = 0.017), while tumor SOX30 mRNA expression was not correlated with OS (P = 0.070)." (PMID 35836594, 2022). "However, in early-stage SCC patients, SOX30 has no inhibitory role on tumor-metastasis due to not binding to CTNNB1 promoter leading to an unfavorable prognosis of the patients." (PMID 30514297, 2018). "Our previous research suggested that SOX30 is a tumor suppressor in ADC but not in SCC." (PMID 29855376, 2018). "However, SOX30 expression was not correlated to age (P = 0.535), gender (P = 0.052), histological grade (P = 0.516), tumor size (P = 0.086) and lymph node status (P = 0.533)." (PMID 26330328, 2015). "However, tumor SOX30 mRNA expression was not correlated with accumulating OS (P = 0.070)." (PMID 35836594, 2022). "Functional analyses indicate that SOX30 strongly inhibits tumor cell metastasis in ADC cell lines, but not affects tumor cell metastasis in SCC cell lines, which is consistent with different association of SOX30 with metastasis in ADC and SCC." (PMID 30514297, 2018). "Downregulation of SOX30 was significantly related to advanced tumor, node, and metastasis (TNM) stages (P = 0.019), but not to age, sex, tumor size, clinical grade, or pathological type." (PMID 29880037, 2018).
cancer (10 papers, 2015 to 2023). A tumor composed of atypical neoplastic, often pleomorphic cells that invade other tissues. "With respect to the association between SOX30 and prognosis in cancers, several studies have disclosed that SOX30 is correlated with a better prognosis." (PMID 35836594, 2022). "In all cases, except for SOX30, the expression of these genes was lower in cancer tissues compared to the healthy ones." (PMID 38132438, 2023). "SOX30 is a recently identified cancer-related member of the SOX family that has a significant role in various types of cancer." (PMID 37829301, 2023). "The study of the literature clearly offers growing evidence of the role of the SOX30 protein in cancer tumorgenesis." (PMID 33152990, 2020). "The up‐regulation of SOX2, SOX4, SOX5, SOX8, SOX9 and SOX18 are found to be associated with poor outcome in different cancer types; however, the up‐regulation of SOX11 and SOX30 is favourable for the prognosis in other cancer types." (PMID 32363730, 2020). "SOX30 is a newly identified cancer-related SOX member that exerts a significant impact on multiple cancer types." (PMID 31889959, 2019). "In human pulmonary malignancies, the SRY-box containing gene 30 (SOX30) is a known cancer-suppressing gene." (PMID 29880037, 2018). "The ability of cancer cell migration was strongly inhibited in SOX30-transfected cells compared with empty vector-transfected cells in A549, SPC-A-1 and LTEP-a-2 cell lines." (PMID 30514297, 2018). "qRT-PCR results suggested that SOX30 expression was significantly lower in 80% (23/30) of the BC tissues than in adjacent cancer tissue." (PMID 29880037, 2018). "The cancer cell invasion ability was also clearly reduced in SOX30-transfected A549, SPC-A-1 and LTEP-a-2 cells." (PMID 30514297, 2018). "To investigate the role of SOX30 on cancer cell metastasis, we generated gain-of-function cell models in ADC cell lines (A549 and SPC-A-1) and SCC cell lines (H520 and H2170) by transfecting SOX30 or empty vector plasmids, and determined cell migration and invasion by transwell assays." (PMID 30514297, 2018). "SOX30 strongly inhibits cancer cell migration and invasion in ADC cell lines, whrereas not affects cell migration and invasion in SCC cell lines." (PMID 30514297, 2018). "To determine SOX30 expression in NSCLC patients, we conducted IHC on a TMA containing 220 cancers." (PMID 26330328, 2015). "Similarly to other SOX proteins, it has also been proved that SOX30 is involved in regulation in the Wnt-signaling pathway by interacting with the CTNNB1 gene (β-catenin) in AC and other types of cancer but not in LSCC cases." (PMID 33152990, 2020).
lung (2 papers, 2015 to 2022). "To further validate the result above, we also analyzed the clinical significance of SOX30 mRNA expression with Kaplan-Meier Plotter in lung ADC and SCC respectively." (PMID 26330328, 2015).
SOX30 also shares sentences with these, for which no sentence is quoted: adenocarcinoma (2 papers); hepatocellular carcinoma (2); Intellectual disability (1); lung squamous-cell carcinoma (1); Lymph Node (1); myelodysplastic syndrome (1); myeloid malignancies (1).